RNF216 (ring finger protein 216)
Description:
[Isoform 1]: E3 ubiquitin ligase which accepts ubiquitin from specific E2 ubiquitin-conjugating enzymes, and then transfers it to substrates promoting their ubiquitination. Plays a role in the regulation of antiviral responses by promoting the degradation of TRAF3, TLR4 and TLR9. In turn, down-regulates NF-kappa-B and IRF3 activation as well as beta interferon production. Also participates in the regulation of autophagy by ubiquitinating BECN1 leading to its degradation and autophagy inhibition. Plays a role in ARC-dependent synaptic plasticity by mediating ARC ubiquitination resulting in its rapid proteasomal degradation. Plays aso an essential role in spermatogenesis and male fertility (By similarity). Mechanistically, regulates meiosis by promoting the degradation of PRKACB through the ubiquitin-mediated lysosome pathway (By similarity). Modulates the gonadotropin-releasing hormone signal pathway by affecting the stability of STAU2 that is required for the microtubule-dependent transport of neuronal RNA from the cell body to the dendrite (By similarity). [Isoform 3]: Inhibits TNF and IL-1 mediated activation of NF-kappa-B. Promotes TNF and RIP mediated apoptosis.
Synonyms: TRIAD3; UBCE7IP1; ZIN; CAHH; U7I1
Tractability: PROTAC: UniProt records ubiquitination sites on it; ubiquitination databases record sites on it.
Gene: Protein-coding gene on chromosome 7 (5,620,047 to 5,781,696, reverse strand). Ensembl gene ENSG00000011275.
Subcellular location: Cytoplasm; Cytoplasmic vesicle, clathrin-coated vesicle
Subcellular location (Human Protein Atlas): Cytosol; Nucleoplasm
Pathways (Reactome):
Immune System: Negative regulators of DDX58/IFIH1 signaling
Gene Ontology:
Molecular function: protein binding; ubiquitin protein ligase activity; zinc ion binding
Biological process: proteasome-mediated ubiquitin-dependent protein catabolic process; protein K48-linked ubiquitination; regulation of defense response to virus by host; regulation of interferon-beta production; negative regulation of type I interferon production; protein ubiquitination
Cellular component: cytosol; nucleus; clathrin-coated vesicle; cytoplasm
Genetic constraint (gnomAD): Loss-of-function variants: 62 observed, 93.55 expected, observed/expected ratio (o/e) 0.66, 90% interval 0.54 to 0.82. The upper end of that interval is the gene's LOEUF score, 0.82, which puts it in group 3 of 6, group 1 being the genes least tolerant of losing a copy. Missense variants: 1,186 observed, 1,053.7 expected, observed/expected ratio (o/e) 1.13, 90% interval 1.07 to 1.18. Synonymous variants: 444 observed, 383.16 expected, observed/expected ratio (o/e) 1.16, 90% interval 1.07 to 1.25.
Homologues: Orthologues: chimpanzee RNF216 (99% identical), macaque RNF216 (96% identical), dog RNF216 (94% identical), pig RNF216 (92% identical), guinea pig RNF216 (89% identical), mouse Rnf216 (87% identical), rat Rnf216 (86% identical), chimpanzee RNF216 (85% identical), rabbit RNF216 (85% identical), tropical clawed frog rnf216 (53% identical), zebrafish rnf216 (42% identical), Caenorhabditis elegans Y57A10A.31 (20% identical). Paralogues in human: RBCK1 (10% identical), SHARPIN (7% identical).
Diseases named in the same sentence as RNF216 in open-access papers:
RNF216 is named in the same sentence as 44 diseases in open-access papers, as found by Europe PMC text mining. Sharing a sentence is not in itself a finding about the gene and the disease. The quoted sentences say what the papers report.
Ataxia (20 papers, 2013 to 2025). Ataxia refers to impaired coordination of voluntary muscle movement. "Here we report a novel homozygous frameshift mutation in RNF216 gene c.1860_1861dupCT (p.Cys621SerfsTer56) in a patient with hypogonadotropic hypogonadism, ataxia, dystonia, and cognitive decline diagnosed with GHS." (PMID 37161390, 2023). "It should be noted that chorea was also described in GHS patients with RNF216 mutations, and ataxia was also found in HDL patients with RNF216 mutations." (PMID 32358900, 2020). "Variants in the RNF216 gene have been linked with hypogonadotropic hypogonadism, ataxia and dementia." (PMID 32982993, 2020). "RNF216, encoding an E3 ubiquitin ligase, has been identified as a causative gene for Gordon Holmes syndrome, characterized by ataxia, dementia, and hypogonadotropic hypogonadism." (PMID 30733708, 2019). "For example, the presence of ataxia and hypogonadotrophic hypogonadism with leukoencephalopathy strongly suggests Gordon Holmes syndrome due to RNF216 mutations." (PMID 28334938, 2017). "In addition to these neuroendocrine abnormalities, GHS individuals with mutations predicted to be deleterious for RNF216 also exhibit ataxia and dementia with corresponding cortical and cerebellar atrophy." (PMID 38164552, 2024). "Here we report a novel homozygous frameshift mutation in RNF216 gene c.1860_1861dupCT (p.Cys621SerfsTer56) in a patient with hypogonadotropic hypogonadism, ataxia, and cognitive decline diagnosed with GHS also co-occurrence of parkinsonism and dystonia which was not reported before." (PMID 37161390, 2023). "Chorea, dementia, and the association of hypodontia, ataxia, hypogonadotropic hypogonadism, and white matter lesions may suggest a RNF216 mutation." (PMID 35222250, 2022). "Homozygous variants predicted to be deleterious such as c.2251C>T and c.2149C→T found within the catalytic domain of RNF216 still display progressive ataxia with cerebellar atrophy indicating regardless of the type of mutation, ataxia is still present." (PMID 38164552, 2024). "A significant enrichment of rare variants in the RNF216 gene was recently shown in patients with CHH and cerebellar ataxia." (PMID 29419413, 2018). "Currently, POLR3A, POLR3B, OTUD4, STUB1, PNPLA6, and RNF216 are all genes associated with CHH syndromes and cerebellar ataxia, with clinical manifestations that can vary and may present with infant or adult onset." (PMID 40508017, 2025). "However, male and female individuals with RNF216 mutations that were predicted to be deleterious still exhibit ataxia, so using Rnf216 KO mice is deemed an appropriate disease model." (PMID 38164552, 2024). "In addition to GHS, RNF216 mutations have been detected in cases with Huntington-like disease (HLD), 4H syndrome (hypodontia, hypomyelination, ataxia and hypogonadotropic hypogonadism), and congenital hypogonadotropic hypogonadism (HH)." (PMID 37161390, 2023). "Furthermore, although 3/4 of our patients had progressive disease, none of the patients showed progressive and debilitating dementia or white matter changes on MRI as reported in RNF216 related ataxia." (PMID 25258038, 2014). "RNF216 is a broadly expressed RBR E3 ligase, and loss‐of‐function mutations in RNF216 are linked to neurodegenerative conditions such as Gordon–Holmes syndrome (GHS) and Huntington‐like disorders, characterized by hypogonadotropic hypogonadism, cerebellar ataxia, and dementia." (PMID 39403837, 2025).
hypogonadotropic hypogonadism (14 papers, 2014 to 2025). Abnormal ovarian or testicular function due to insufficient hormonal stimulation from the hypothalamic-pituitary axis. "However, it is still elusive how deficiency in RNF216 leads to hypogonadotropic hypogonadism." (PMID 30733708, 2019). "Other rare and novel pathogenic variants in ANOS1, WDR11, FGFR1, RNF216, and CHD7 genes were also found in patients with Congenital Hypogonadotropic Hypogonadism." (PMID 38637882, 2024). "We thus have identified that RNF216 regulates the migration of GnRH neuron by suppressing Beclin1 mediated autophagy, and indicated a potential contribution of autophagy to the hypogonadotropic hypogonadism." (PMID 30733708, 2019).
Gordon Holmes syndrome (12 papers, 2017 to 2025). "RNF216 (E3 ubiquitin ligase) is involved in ubiquitin–proteasome system, and its mutations are associated with a rare neurodegenerative disorder known as Gordon Holmes syndrome." (PMID 40495047, 2025). "Here we present a case with Gordon Holmes syndrome caused by a novel RNF216 mutation." (PMID 37161390, 2023). "Mutations in the RNF216 (ring finger protein 216) gene alone or in combination with mutations in OTUD4 (OTU deubiquitinase 4), which are involved in ubiquination, are the cause of Gordon Holmes syndrome." (PMID 33917666, 2021). "This phenotype was rescued by co-injection with human RNF216 mRNA but not with the human mRNA with mutations related to Gordon Holmes syndrome." (PMID 33917666, 2021). "Similarly, although RNF216 (TRIAD3), another RBR-type E3, has been linked to the neurodegenerative disorder Gordon–Holmes syndrome and its activity is enhanced by phosphorylation and K63-linked di-Ub, neither the subcellular localization of the activated protein nor its substrates are known." (PMID 36563856, 2022).
dementia (10 papers, 2014 to 2025). Loss of intellectual abilities interfering with an individual's social and occupational functions. "Because GHS individuals with RNF216 mutations exhibit dementia, we reasoned that Rnf216 KO mice would develop impairments in spatial learning and memory." (PMID 38164552, 2024). "Interestingly, a combination of mutations in OTUD4 along with mutations in RNF216, which codes for a ubiquitin ligase, was also found to result in dementia." (PMID 37149835, 2023). "Although all three Gordon Holmes associated genes (RNF216, OTUD4, STUB1) play a role in the ubiquitin system, the presence of dementia and white matter lesions on MRI has so far only been observed with RNF216/OTUD4 mutations, illustrating some phenotypic diversity related to this syndrome." (PMID 25258038, 2014).
colorectal cancer (4 papers, 2016 to 2021). A primary or metastatic malignant neoplasm that affects the colon or rectum. "In this study, we found that RNF216 was upregulated in human colorectal cancer (CRC) tissues and cell lines, and was associated with progression of CRC." (PMID 27203674, 2016). "RNF216 expression is associated with poor survival in colorectal cancer and ovarian carcinoma, although whether over- or under-expression decreases survival is unknown." (PMID 34090518, 2021). "In another study, the ring figure protein 216 (RNF216) promoted colorectal cancer cell migration by enhancing proteasomal degradation of BECN1." (PMID 31272261, 2019).
hypogonadism (4 papers, 2013 to 2019). A disorder characterized by decreased function of the gonads. "Recently, reports have linked mutations in genes involved in ubiquitination (RNF216, OTUD4, STUB1) to ARCA with hypogonadism." (PMID 25258038, 2014).
cognitive decline (3 papers, 2017 to 2023). "We identified a novel homozygous nonsense mutation in RNF216 in a 42-year-old male with slowly progressive cognitive decline, gait impairment and erectile dysfunction, starting at age 31 years." (PMID 28334938, 2017).
bipolar disorder (2 papers, 2025). A disorder of the brain that causes unusual shifts in mood, energy, activity levels and the ability to carry out day-to-day tasks. "Exploration of rare copy-number variants in 1839 patients suffering from bipolar disorder compared to 2760 controls revealed RNF216 significantly associated with bipolar disorder." (PMID 40430072, 2025).
leukodystrophy (2 papers, 2021 to 2024). Leukodystrophies are a group of rare, progressive, metabolic, genetic diseases that affect the brain, spinal cord and often the peripheral nerves. "This underlines the limitation of panel sequencing, which unlike WES or WGS, does not allow for future re-analysis of DNA to detect for mutations in leukodystrophy genes that are discovered after initial panel curation (in this case the CLCN2, AARS, CTSA, and RNF216 genes)." (PMID 33597917, 2021).
viral infection (2 papers, 2022 to 2025). "For instance, RNF216 or SKP2 promotes K48-ubiquitination and destabilization of Beclin 1 to inhibit autophagy in response to pathogen or viral infection." (PMID 36528652, 2022).
colon cancer (1 paper, 2018). "Ring family ubiquitin ligase RNF216 (ring-finger protein-216) is another protein which suppresses autophagy by inducing K48-linked poly-ubiquitination and degradation of BECN1 in TLR-stimulated macrophages and colon cancer." (PMID 30370269, 2018).
diabetes (1 paper, 2013). "Triad3A (RNF216) was significantly higher in diabetes and may have contributed to reduced levels of TLR4 protein." (PMID 23149823, 2013).
endothelial dysfunction (1 paper, 2025). In vascular diseases, endothelial dysfunction is a systemic pathological state of the endothelium (the inner lining of blood vessels) and can be broadly defined as an imbalance between vasodilating and vasoconstricting substances produced by (or acting on) the endothelium. "These included genes such as CLNS1A, UGP2, RNF216, PHGDH, CKAP4, and IL6R, many of which are known to participate in inflammatory pathways, oxidative stress, and endothelial dysfunction." (PMID 41262879, 2025).
generalized seizures (1 paper, 2025). "RNF216 involvement following generalized seizures may be linked to its functions in protein ubiquitination and degradation pathways, which are crucial for maintaining cellular homeostasis and regulating immune responses." (PMID 40495047, 2025).
glioblastoma (1 paper, 2024). The most malignant astrocytic tumor (WHO grade IV).
leukemia (1 paper, 2025). A malignant (clonal) hematologic disorder, involving hematopoietic stem cells and characterized by the presence of primitive or atypical myeloid or lymphoid cells in the bone marrow and the blood. "Several of the top 20 APL super enhancers are linked to genes known to have functional roles in leukemia, for example RNF216, FSCN1, FNDC3B, HSP90B1, C12orf75, and JARID2, among them, JARID2 is a hematopoietic tumor suppressor through recruiting PRC2 to repress self-renewal pathways." (PMID 41168841, 2025).
male infertility (1 paper, 2025). The inability of the male to effect fertilization of an ovum after a specified period of unprotected intercourse. "Notably, several SNPs associated with parental interaction effects in the ART sample mapped to genes previously implicated in male infertility, including ACTB, FSCN1, and RNF216." (PMID 41325449, 2025).
metastasis (1 paper, 2016). The spread or migration of cancer cells from one part of the body (where they first appeared) to another. "RNF216 expression is positively associated with patients' characteristics, including advanced clinical stage, tumor size and positive lymph node metastasis, highlighting its potential for use in diagnosis and therapeutic guidance." (PMID 27203674, 2016).
tumor (4 papers, 2014 to 2026). "The expression levels of RNF216 vary in tumor mutational burden (TMB) and microsatellite instability (MSI) across different tumors." (PMID 41869446, 2026). "The protein-protein interaction (PPI) network and GSCALite suggested that RNF216 and its co-expressed genes may promote tumor growth by regulating mitosis, cell death, and DNA damage." (PMID 41869446, 2026). "Our data showed that high RNF216 level negatively correlated with BECN1 expression, consistent with the role of BECN1 as a tumor suppressor." (PMID 27203674, 2016). "In summary, our study found that RNF216 expression is increased in CRC tissues and correlates with clinical stage, tumor size and positive lymph node metastasis." (PMID 27203674, 2016). "RNF216 promoted CRC cell proliferation and migration in vitro and in vivo, largely by enhancing proteasomal degradation of BECN1, a key autophagy regulator and tumor suppressor." (PMID 27203674, 2016).
cancer (3 papers, 2016 to 2026). A tumor composed of atypical neoplastic, often pleomorphic cells that invade other tissues. "Although RNF216 has several interaction partners, such as TLR4, RIP1, TRAF3 and BECN1, our data showed that only BECN1 was significantly upregulated in CRC cells in response to RNF216 knockdown, supporting that RNF216 contributes to cancer development by regulating autophagy." (PMID 27203674, 2016). "Previous studies have reported that RNF14, RNF31, RNF144B, RNF216 and ARIH1 mainly play carcinogenic roles, while ARIH2 and PARK2 generally play anticancer roles in malignant tumors." (PMID 35732617, 2022). "Moreover, monoallelic loss of the essential autophagy gene BECN1 causes susceptibility to metabolic and promotes tumorigenesis, which is consistent with our observations that RNF216 could enhance BECN1 degradation dampening autophagy and contributing to cancer cells proliferation." (PMID 27203674, 2016).
RNF216 also shares sentences with these, for which no sentence is quoted: cerebellar ataxia (6 papers); cognitive defects (2); congenital hypogonadotropic hypogonadism (2); Hypodontia (2); acute respiratory distress syndrome (1); autism (1); Baraitser-Winter syndrome 1 (1); Cerebellar atrophy (1); Chorea (1); Dystonia (1); erectile dysfunction (1); frontotemporal dementia (1); infection (1); Leukoencephalopathy (1); lung injury (1); major depressive disorder (1); Mental retardation, autosomal dominant 48 (1); microphthalmia (1); movement disorder (1); neurodegenerative disease (1); neurological diseases (1); osteogenesis imperfecta (1); ovarian carcinoma (1); Parkinsonism (1).